TNF (tumor necrosis factor)
Diseases named in the same sentence as TNF in open-access papers (continued):
Sharing a sentence is not in itself a finding about the gene and the disease.
tumor (continued). "However, the kinetics of taxane-induced TNF-α induction in human tumor cells are remarkably distinct from macrophages, as the latter requires drug concentrations in the 1 to 10 μM range, producing a maximal response within 90 minutes." (PMID 28915246, 2017). "Furthermore, we also checked the level of TNF-α, an important indicator of anti-tumor systemic immune responses, in sera of mice at day 9th post the irradiation of primary tumors." (PMID 29026068, 2017). "Likewise, studies have shown that the combination of the T-helper cell cytokines, IFNγ and TNFα, or genotoxic drugs induces tumor cell senescence and involves the JAK/STAT pathway." (PMID 29176033, 2017). "Besides the impact of TNFα on immune cells, there is strong evidence of a direct interaction of TNFα with tumor cells." (PMID 28160574, 2017). "Moreover, increased TNF-α and myostatin concentrations are often detected in tumor-bearing animals and cancer cachexic patents." (PMID 29069832, 2017). "We postulate that the release of cell debris from the tumor to the blood as a result of the hyperthermic tumor treatment might lead to a systemic release of cytokines (e.g. IL-1, TNF-α, IL-6)." (PMID 28761146, 2017). "NF-κB activation in tumor cells can promotes tumor progression by enhancing their aggressive potential and increase the transcriptions of proinflammatory and angiogenetic genes, for example IL-12, TNF-α and iNOS." (PMID 28804688, 2017). "Tumor-derived TNFα can function in an autocrine mode as well as paracrine manners." (PMID 28900035, 2017). "Similarly, TNFα was shown to limit tumor growth independently as well as though activation of anti-tumor immunity in neutrophils." (PMID 29340117, 2017). "Moreover, the Vax/aGITR/aPD-1 therapy showed a synergistic effect, as illustrated by the higher frequency of OVA-specific IFNγ/TNFα dual-positive CD8+ T cells within the tumor." (PMID 28388572, 2017). "TNFα production was achieved using MG-TNFα as evidenced by analysis of tumour extracts." (PMID 28662099, 2017). "Research has shown that cytokines that are present at constitutively high levels as a product of chronic inflammation, such as TNF-α and IL-6, may promote tumor cell proliferation." (PMID 29201631, 2017). "Interestingly, tumor microenvironment produces cytokines, chemokines and growth factors, including TNFα, TGFβ, IL-6, FGF, epidermal growth factor (EGF), and HGF." (PMID 29088851, 2017). "Furthermore, we demonstrate that the inhibition of tumor progression from DCIS to IDC is mediated by the suppression of local production of the inflammatory cytokines IL-6 and TNFα, within the tumor and mammary tissue." (PMID 28416734, 2017). "The percentage of total CD8s that were antigen specific and capable of producing IFNγ and TNFα was 5 to 15% in spleens and 5 to 15% in tumors, respectively, indicating significant expansion of antigen-specific lymphocytes in the tumor and the peripheral reservoir." (PMID 28649380, 2017). "Thus, an important question remained, namely: to which extent does LPS or the downstream effector molecule TNF-α constitute components responsible for an intrinsic bacterial anti-tumor effect?" (PMID 28445131, 2017). "Therefore, we examined the expression of IFN-γ and TNF-α in tumor tissues treated with oncolytic Ads." (PMID 28002796, 2017). "Because TNF-α is induced as a proinflammatory cytokine and activates NF-κB at molecular level in cells, all the proinflammatory cytokines and chemokines are now understood to be endogenous tumor promoters in human carcinogenesis." (PMID 28124725, 2017). "Most of the bacteria (for instance B. xylanisolvens, Paraprevotella clara, Prevotella timonensis) were positively relating with anti-inflammatory/tumor markers (e.g. Trem-2, MR, arginase-1, TNF-α) and negatively correlating with pro-inflammatory/tumor markers (e.g. IL-12, IL-6 and iNOS)." (PMID 28970547, 2017).
tumor (continued). "An engineered TNFα producing construct deployed in mouse models via either intra-tumoural (i.t.)or intravenous (i.v.)administration facilitated robust TNFα production, as evidenced by ELISA of tumour extracts." (PMID 28662099, 2017). "In the mouse model for tumor growth, 7E inhibited both TNF-α expression and tumor growth." (PMID 29242565, 2017). "Moreover, low doses of TNF-α have been shown to promote antitumor immune responses by enhancing T-cell infiltration and by activating macrophages toward a tumor-suppressive phenotype." (PMID 29276511, 2017). "Thus bioenergetic responses of epithelial cells from tumor‐affected and non‐affected breasts are different to TNFα." (PMID 28369883, 2017). "Tumor-infiltrating DCs were slightly, yet significantly, increased in WT mice treated with anti-PD-1 as well as in TNF-deficient mice with or without anti-PD-1 injection." (PMID 29273790, 2017). "In addition, circulating neutrophils produce inflammatory mediators such as tumor necrosis factor and interleukin, which promote tumor cell proliferation and angiogenesis." (PMID 28052031, 2017). "Emerging evidence indicates that tumor-promoting macrophages support cancer stem cell renewal, maintenance, and migratory capacity through the secretion of numerous factors including IL-6 and TNFα." (PMID 28881599, 2017). "It was therefore of interest to determine whether inhibition of TLR4 signaling with either penta-acylated LPS from R. Sphaeroides (LPS-RS) or TAK-242 would inhibit docetaxel-induced TNF-α release in tumor cells." (PMID 28915246, 2017). "TNF pathway could be activated by various signals to affect the immunity, cell growth, apoptosis and other biological behaviors of tumor cells." (PMID 28384236, 2017). "The current results, along with our previous report, suggest that RMS cancers may respond to combination therapy with SMCs and a pro-death ligand (e.g. TNFα) to promote the elimination of tumour cells." (PMID 27966453, 2017). "Moving on to TNF, TNFα is a double-edged sword in tumor development." (PMID 28599664, 2017). "TNF-α also enhances tumor angiogenesis through increasing production of VEGF and basic FGF-2." (PMID 28883992, 2017). "Although, TNF-α is able to induce tumor cell death, its primary role is pro-inflammatory." (PMID 28278159, 2017). "However, as the association between chronic inflammation and cancer is now appreciated, TNF-α, a master mediator of inflammation, enhances tumor development and spread." (PMID 29069789, 2017). "In addition, the cytokines produced by activated innate immune cells in tumor microenvironment can stimulate tumorigenesis, such as IL-6 and TNF-α." (PMID 28630636, 2017). "Low levels of TNF-α in this study, is a good indicator of the antitumor potential of licorice polysaccharides which inhibited its production and circulation, thereby affecting and suppressing tumor growth." (PMID 29246138, 2017). "Although high-dose irradiation might directly inhibit functions of DCs, another study showed that irradiation (3 × 5 Gy) induced tumor cell death that triggers DC maturation and production of proinflammatory cytokines such as IL-6, IL-8, IL-12p70, and TNF-α." (PMID 28603525, 2017). "Taken these data together, GSC might potentiate TNFα inducing apoptosis of tumor cell and reduce the possible inflammatory side effects by NF-κB activity suppression." (PMID 29379440, 2017). "β-glucans from shiitake can augment phagocytosis, ConA-induced splenocyte proliferation, DTH reactions, TNF-α and IFN-γ production and finally NO production in peritoneal macrophages, that might be underlying mechanisms explaining their anti-tumour effects." (PMID 29249921, 2017). "Thereby, the anti-inflammatory impact of vagus nerve fibers on tumor infiltrating macrophages and TNFα suppression may get lost." (PMID 28160574, 2017).
tumor (continued). "Alternatively, lack of SM-induced autocrine TNF secretion could be compensated by activating complementary TNF-producing pathways in cancer or other cell types in the tumor environment." (PMID 28771230, 2017). "Interestingly, proliferation of both tumor cell lines was significantly reduced when cultured in CM of IFNγ- and TNFα-activated microglia (p < 0.001, ratios 0.51 and 0.49), but not by TGFβ1-treated microglial CM (ratios 0.98 and 1.05)." (PMID 28008153, 2017). "It was therefore of interest to determine whether similar mechanisms are employed during the processing of drug-induced TNF-α release in epithelial-derived tumor cell lines." (PMID 28915246, 2017). "In addition, SDF-1 attracts pDCs to the tumor environment, where they induced angiogenesis through production of TNF-α and IL-8 to promote ovarian tumor angiogenesis." (PMID 29085361, 2017). "However, a significant increase (p = 0.0414) of TNFα expression was detectable in tumor tissue after vagotomy compared to the sham group." (PMID 28160574, 2017). "The non-pathogenic E. coli strain MG1655 was investigated as a tumour targeting system in order to produce TNFα specifically within murine tumours." (PMID 28662099, 2017). "TNF-α and IL-6 activate each other to form the cytokine network in tumor tissues." (PMID 28825631, 2017). "However, both IFN-γ and TNF-α expression was significantly higher in RdB/IL12/DCN-treated tumor tissues." (PMID 28002796, 2017). "NF-κB is extensively studied in TNF-α-induced tumor initiation and progression." (PMID 29238068, 2017). "As microglia treated by IFNγ and TNFα supposedly represent a population of M1 activated microglia and TGFβ1 treated cells a subpopulation of M2 activated microglia, the tumor cells in our experimental system seem to shift microglia towards a more M2-like phenotype." (PMID 28008153, 2017). "The impact on tumor growth was monitored in wild type and TNFα −/− mice using MRI." (PMID 28160574, 2017). "TNF-α represents an important readout for the tumor therapeutic effects and a systemic response." (PMID 28637010, 2017). "Tumor necrosis factor-alpha (TNF-α), a critical proinflammatory cytokine intensively studied in the immune system, is also established to regulate the process of immunity, cell homeostasis, and tumor progression." (PMID 29238068, 2017). "Additionally, TNF-α activates the major inflammatory response pathway NF-kB, which facilitates both tumor development and metastatic progression." (PMID 29379795, 2017). "Similarly, low doses of tumor necrosis factor-α (TNF-α) normalized tumor blood vessels and improved adoptive T cell transfer therapy." (PMID 28665313, 2017). "In summary, based on our in vitro and in vivo data, we identified in human GC an immunosuppressive pathway, which leads to CD45RA−CCR7− Treg subset induction by tumor-derived TNF-α and subsequent CD8+ T cells’ suppression and correlates with tumor progression and poor survival." (PMID 28817117, 2017). "Crucial contributions of TNF-α/TNF-R in tumor initiation and progression have been suggested." (PMID 28852270, 2017). "However, there was a significant increase in the level of TNF-α mRNA in tumor tissue and Her2-specific Ab (antibody) production." (PMID 28489607, 2017). "As a tumor promoter, TNF-α activates Noxo1 and Gna14 to enhance gastric tumorigenesis." (PMID 28938560, 2017). "In current study, we found that GSC attenuated NF-κB activity, inhibited its translocation in nucleus and induced synergistic increase with TNFα of A549 cell apoptosis, which was in line with previous reports that inhibition of NF-κB activation increased TNFα inducing tumor cell apoptosis." (PMID 29379440, 2017). "Accordingly, in the murine experimental model of colitis-associated cancer (CAC), both the tumor multiplicity and growth were diminished in the absence of IL-17A, IL-6, IL-11 or TNF-α." (PMID 28881574, 2017).
tumor (continued). "Consequently, we found increased levels of TNFα within the tumor following vagotomy suggesting that the vagal nerve had a direct influence on macrophages within tumor tissues, modulating the local cytokine milieu." (PMID 28160574, 2017). "To address this, following tumor inoculation we measured global cytokine mRNA differences, including TGFβ, TNFα, IL-10 and IFNγ, between WTTU and L3TU groups on day 5, the time point where we observed the greatest differences in cellular accumulation and CD69 positivity." (PMID 29109732, 2017). "Other positive effects of TNF-α and IL-1β release stems from the fact that prior work from our laboratory demonstrated that both cytokines are necessary to restore the mixed lymphocyte reaction ability of DCs after phagocytosis of tumor irradiated cells." (PMID 29109725, 2017). "Moreover, TNF and IL-6 directly control and contribute to tumor promotion in early lesions of ApcMin/+ mice by inhibition of apoptosis and up-regulation of angiogenic mediators." (PMID 28881611, 2017). "Given the reported ability of TNF-α to sensitize tumor cells to taxanes, the docetaxel-sensitizing effects observed here may likewise be provoked through LPS's ability to induce TNF-α production and subsequent death-associated autocrine signaling." (PMID 28915246, 2017). "Furthermore, in severe combined immunodeficient mice with orthotopically growing PDAC tumors, the human-specific anti-TNF antibody infliximab reduced tumor growth and metastasis by about 30% and 50%, respectively." (PMID 27542263, 2017). "Notably, the SMC-mediated effects on eliciting death of CT-2A cells were mainly dependent on TNF-α (the primary mediator of SMC-induced tumour killing)." (PMID 28198370, 2017). "Moreover, tumor vessel permeability changes were detected in a group of mice treated with TNF-α (100 μL of TNF-α at 10 μg/mL), a drug used in clinical trials that is known to increase vascular permeability." (PMID 28783106, 2017). "When inflammation occurs, tumor cells, macrophages, and other tumor infiltrating immune cells possess high reactive oxygen species (ROS), and secrete chemokines and cytokines such as IL-6, tumor necrosis factor (TNF)-α, IL-1β, IL-10, and transforming growth factor (TGF)-β to tumor microenvironment." (PMID 28629173, 2017). "The pronounced TNFα release by ChA-treated M1 and the fact that TNFα mediates apoptosis and tumour cytotoxicity prompted to investigate whether TNFα might contribute to the decreased viability of MCF-7 cells in the ChA-treated M1 model." (PMID 28134280, 2017). "Our findings propose that when the TME is enriched with both cytokines, as may often be the case in malignancy, TNFα + TGFβ1 would act not only on the tumor cells but also may induce the release of pro-inflammatory and tumor-promoting factors by MSCs." (PMID 28553282, 2017). "Recent data indicate that endocrine dysfunction in patients with MG may be related to the production of growth factors as well as of cytokines such as IGFBP-2 and IGFBP-3, VEGF, IL-1β, IL-6, and TNF-α by tumor cells or their microenvironment." (PMID 28740334, 2017). "In the process of tumour development or metastasis, cancer cells can become resistant to TNF-α." (PMID 28149533, 2017). "Mice with either 4T07 or 4T1 tumors had increased liver mRNA production of IL-1β (H = 34.10, p < 0.001), IL-6 (H = 29.12, p < 0.001), and TNFα (H = 35.31, p < 0.001) compared to either the vehicle or 67NR tumor-bearing mice (p < 0.05 in all cases, Dunn’s multiple comparisons)." (PMID 28811490, 2017). "In contrast, a paradoxical tumor-promoting role of TNF has also become apparent." (PMID 28158970, 2017).
tumor (continued). "Whereas some studies have demonstrated that high concentrations of TNF-α reduce tumour angiogenesis in neoplastic tissues, other studies have demonstrated that TNF-α may operate as an endogenous tumour growth factor." (PMID 29089667, 2017). "The concentrations of IL-2 and TNF-α also play an important role in the immune function, which may enhance the ability of tumor controlling for cancer patients." (PMID 29259647, 2017). "Not only can circulating neutrophil levels rise, but neutrophils can localize to the tumor due to multiple factors, including general inflammatory signals like IL-1 and TNF-alpha, as well as IL-8 release triggered by hypoxic conditions of the tumor microenvironment." (PMID 28418870, 2017). "The NGF antitumor mechanism may cause an increase of lymphocytic infiltration in the tumor, a rise in the levels of IL-1β and TNF-α in the serum of tumor-bearing mice, and an increase in aerobic glycolysis." (PMID 28878143, 2017). "It has been reported that TNF-α promotes gastric tumorigenesis and tumor lymphangiogenesis." (PMID 28938560, 2017). "Earlier reports indicated that IL-6 and TNF-α have a tumor-promoting effect." (PMID 28969049, 2017). "In summary, our results indicate that the tumor-promoting role of prostatic TAMs may be partially ascribed to up-regulation of let-7b, which regulates expression of IL-12, IL-23, IL-10 and TNF-α." (PMID 27157642, 2016). "Some cytokines, such as tumor necrosis factor α (TNF-α), promote tumor growth by activating NF-κB." (PMID 26973522, 2016). "Higher expressions of TNF-α have been reported in various tumour tissues." (PMID 26881177, 2016). "While these preliminary studies have been promising, our investigations suggest that the use of the combination of vectors expressing IFN-γ and TNF-α could potentiate the anti-tumor response." (PMID 27211104, 2016). "Tumor-producing TNFα has been shown to induce tumor cell death in an autocrine manner." (PMID 27014915, 2016). "Presence of micrometastatic tumor cells in the liver may induce the Kupffer cells to produce a variety of cytokines (IL-1, IL-6, and TNF-a), which may modulate albumin synthesis by hepatocytes." (PMID 26880857, 2016). "Here, using in vitro and in vivo study, we investigated whether radiotherapy enhanced the therapeutic effect of TNF-α activated AD-MSCs by monitoring the tumor growth, survival rate, metastasis and regulatory T cell population in spleen and local lymph node." (PMID 27329316, 2016). "Since both MCT and MCTC infiltrating tumour islets in ES NSCLC patients express TNFα, the cytotoxic activity of this cytokine may confer improved survival in these patients." (PMID 27922077, 2016). "Moreover, ascophyllan induced activation of dendritic cells (DCs), and promoted IFN-γ- and TNF-α-producing Th1 immune responses in tumor-bearing mice." (PMID 27008707, 2016). "Besides, some cytokines (TNF-α and INFγ) have been shown to be efficient in inhibiting exponential growth of tumor cells, aiding in their elimination." (PMID 27574962, 2016). "We here chose 1 μg/mouse for TNFα which could partly inhibit tumor growth and avoid masking the action of combined treatment of TCP-1/TNFα and TCP-1/IFNγ." (PMID 27342639, 2016). "IL-10 associated with GBM is shown to enhance tumor growth, inhibit production of IFN-γ and tumor necrosis factor-alpha (TNF-α) by the immune system, downregulate expression of MHC class II in monocytes, and, via the co-stimulatory CD28-CD80/86 pathway, induce anergy in infiltrating T-cells." (PMID 26973839, 2016). "It is very tempting to suggest that such a mechanism with activated monocytes could target tumor cells in a TNF-mediated mechanism." (PMID 27882334, 2016). "Natural killer (NK), cytotoxic T cells, and gamma-delta T cells are critical cellular effectors of the immune system, which can recognize and kill virus-infected and tumor-transformed cells and can also release chemokines and cytokines, such as tumor necrosis factor-alpha (TNF-α)." (PMID 28154561, 2016).